RAB4B-EGLN2 (RAB4B-EGLN2 readthrough (NMD candidate))
Synonyms: RERT-lncRNA
Gene: Protein-coding gene on chromosome 19 (40,778,242 to 40,808,418, forward strand). Ensembl gene ENSG00000171570.
Genetic constraint (gnomAD): Missense variants: 244 observed, 292.11 expected, observed/expected ratio (o/e) 0.84, 90% interval 0.75 to 0.93. Synonymous variants: 108 observed, 119.35 expected, observed/expected ratio (o/e) 0.9, 90% interval 0.77 to 1.06.